IL6 (interleukin 6)
Diseases named in the same sentence as IL6 in open-access papers (continued):
Sharing a sentence is not in itself a finding about the gene and the disease.
Sepsis (continued). "Previous studies have observed correlations between sepsis severity and serum levels of IL-6 and PCT." (PMID 39589972, 2024). "A study examining how NAC treatment affects changes induced by sepsis in conscious rats revealed a reduction in inflammatory biomarkers (IL-6, tumor necrosis factor-α (TNF-α), and IL-10) linked to sepsis." (PMID 39064168, 2024). "Among the 29 patients identified by IL-6 as having sepsis, 16 were confirmed to have developed sepsis." (PMID 38849783, 2024). "IL-6 is a crucial cytokine involved in the innate immune response in sepsis, contributing to adverse outcomes in tandem with other pathophysiological processes." (PMID 38698853, 2024). "Specifically, hepatic HNF4α failure in sepsis mediates lipid dysfunction, downregulates several nuclear receptors, including PPARα, and diminishes IL6-mediated acute phase signaling." (PMID 39261648, 2024). "Normally, serum concentrations of IL-6 range from 1 to 25 pg/mL, but in sepsis, they can exceed 1 ng/mL." (PMID 39201697, 2024). "In sepsis, IL-6 peaks around two hours after infectious stimulation and remains persistently elevated, often exceeding 500 pg/mL." (PMID 39589972, 2024). "IL-6 has been shown to predict fatal or severe sepsis in premature infants, which occurs more often in Gram-negative than Gram-positive infections due to pathogen virulence factors." (PMID 38312920, 2024). "Elevated lactate levels as a marker for transition from simple infection to sepsis and switch from aerobic to anaerobic glycolysis, as well as inflammatory markers such as interleukin-6 have been reported to promote sympathetic outflow." (PMID 39128824, 2024). "A single-strain probiotic in children with acute lung injury in China reduced both TNF-α and IL-6, and a multi-strain probiotic in children with severe sepsis in India beneficially affected a number of inflammatory cytokines." (PMID 38337621, 2024). "In neonatal medicine, interleukins like IL-6, IL-8, IL-10, and IL-12 are employed as biomarkers for diagnosing conditions such as sepsis." (PMID 38251210, 2024). "While the expression of proinflammatory factors in sepsis (IL-6, IL-1β and TNF-α), which contributed to septic shock, were decreased." (PMID 38166628, 2024). "Sepsis can lead to the excessive production of pro-inflammatory cytokines such as interleukin-6 (IL-6), interleukin-1 beta (IL-1β), and tumor necrosis factor-alpha (TNF-α)." (PMID 39273060, 2024). "Serum suPAR, together with other inflammatory markers IL-6, IL-16, CRP, and CCL3, was associated to the severity of sepsis-induced acute kidney injury." (PMID 39540961, 2024). "The JAK/STAT pathway is a prominent signaling cascade activated by several critical cytokines implicated in sepsis, such as IFN-γ, IL-4, IL-6, IL-10, and IL-12." (PMID 39062636, 2024). "Nowadays, traditional biomarkers such as CRP, PCT and IL-6 are widely used in the diagnosis and evaluation of sepsis." (PMID 39371337, 2024). "BMP6 did not correlate with leukocyte numbers, procalcitonin, CRP, or IL-6 in the sepsis/septic shock group (p > 0.05 for all) or in the SIRS/sepsis/septic shock cohort when patients with liver cirrhosis were excluded." (PMID 39200147, 2024). "In healthy adults, IL-6 concentrations typically range from 0 to 43.5 pg/mL, but in sepsis or septic shock, levels can exceed 3500 pg/mL." (PMID 39407738, 2024). "The levels of IL-10 and IL-6 are elevated in sepsis, indicating a mixed hyperinflammatory and immunosuppressed status." (PMID 38696304, 2024). "The markers of M1 macrophage activation, TNF-α and IL-6, are significantly elevated in sepsis (Fig. EV4G)." (PMID 39294473, 2024). "As an endogenous pyrogen, it can promote fever, cause apoptosis, induce sepsis by inducing the production of IL1 and IL6, induce dysplasia, induce inflammation, prevent tumorigenesis and viral replication." (PMID 38606290, 2024).
Sepsis (continued). "IL-6 and IL-10, which have better predictive ability for sepsis among all immune response biomarkers, as well as CRP, PCT and clinical scores were selected for further analysis of their relationship with secondary endpoints." (PMID 39212218, 2024). "The immune response in COVID-19 sepsis is believed to differ significantly from bacterial immunity, characterized by a delayed and less severe response, as indicated by IL-6 serum concentrations." (PMID 38779663, 2024). "IL-6 is one of the most studied cytokines in sepsis; its circulating levels rise rapidly in response to infection within 2 h after the onset of bacteremia, with a peak at approximately 6 h, and finally declining over the following 24 h." (PMID 38535886, 2024). "TNF-α, IL-1β and IL-6 are pro-inflammatory cytokines that play a central role in the pathogenesis of sepsis." (PMID 39885929, 2024). "IL-6 was found to be superior to CRP in the prediction of sepsis 1 or more days before clinical diagnosis." (PMID 38671704, 2024). "In sepsis, B cells can produce a variety of pro-inflammatory cytokines like IL-6, TNF, IL-3, and GM-CSF, which amplify the systemic inflammatory response." (PMID 39664383, 2024). "Specifically, our findings demonstrate that LBT exerts a significant inhibitory effect on lipopolysaccharide (LPS)-induced sepsis by suppressing the expression of key pro-inflammatory cytokines such as IL-6, TNF-α, and IL-1β." (PMID 38799158, 2024). "The results of studies on patients with sepsis are consistent with our findings: the higher the level of IL-6 at the onset of sepsis, the worse the prognosis." (PMID 39212218, 2024). "The aim of this study was to assess the efficacy of an IL-6 blockade with tocilizumab on the treatment outcome of sepsis/septic shock in children with febrile neutropenia." (PMID 38672594, 2024). "Pro-inflammatory cytokines, particularly interleukin-1 (IL-1) and interleukin-6 (IL-6), play a pivotal role in the pathogenesis of sepsis-induced organ damage, including kidney injury." (PMID 39859942, 2024). "Despite several reports on its use for sepsis prognosis, IL-6 is still incompletely evaluated as a prognosis marker in sepsis and inflammation." (PMID 39202614, 2024). "As a pro-inflammatory cytokine, IL-6 has been reported to be a prominent prognostic marker for assessing the severity of sepsis, and its clinical significance has been extensively investigated in various septic conditions through numberous studies." (PMID 39686985, 2024). "Another objective of the study revealed that IL-6 correlates with other sepsis markers, showing significant correlations with APTT, anion gap, and lactate." (PMID 39589972, 2024). "Various proinflammatory cytokines, such as TNF-α and IL-6, can induce cardiac dysfunction during sepsis and subsequently lead to heart failure." (PMID 39664383, 2024). "An association between elevated IL-6 values and mortality was demonstrated in previous studies, for example in patients with sepsis, which is why the current study additionally focused on IL-6 in this comparison of biomarkers." (PMID 38336628, 2024). "Peg13 mitigates the inflammatory response by reducing the release of proinflammatory cytokines HMGB1 and IL-6 in sepsis, presenting a potential therapeutic target for alleviating inflammation in sepsis treatment." (PMID 38856110, 2024). "We constructed a nomogram depicting the TAPSE/PASP in conjunction with IL-6 and Lac for the joint prediction of sepsis prognosis, and demonstrated the highest predictive capability (AUC = 0.878, 95% CI 0.809–0.948)." (PMID 38961249, 2024). "When macrophages release excessive amounts of pro-inflammatory cytokines such as TNF-α, IL-1, and IL-6 in an uncontrolled manner, it can lead to a severe inflammatory response known as a cytokine storm, which can progress to severe sepsis." (PMID 39337575, 2024). "They found that IL-6 and procalcitonin were more predictive of sepsis severity and mortality compared to CRP." (PMID 39063926, 2024).
Sepsis (continued). "By decorating the corresponding antibodies on the surface of barcodes, the microneedle sensors showed accurate, specific and multiplexed detection of TNF‐α, IL‐1β and IL‐6 in a sepsis mice model." (PMID 38225744, 2024). "The persistent presence of IL-6 is inversely correlated with survival rates in patients with bacterial sepsis and septic shock, indicating that IL-6 plays a significant role in the progression and poor outcome of sepsis." (PMID 39056754, 2024). "Our in vitro data is supported by clinical data that show comparable serum levels of TNF-α and IL-6 during sepsis between preterm newborns, term newborns and adults." (PMID 38562936, 2024). "With regard to PICU mortality in patients with cancer-related sepsis, need mechanical ventilation, acute liver failure, higher IL-6 level, hypoalbuminemia, and higher inotropic support were associated with a higher PICU mortality." (PMID 38797509, 2024). "We also observed a more prominent inflammatory response in severe sepsis than in mild sepsis, with higher levels of IL-6 and IL-10 in 7 or 10-punctures CLP than in 4-punctures CLP." (PMID 39522078, 2024). "Interleukin 6 is a proinflammatory cytokine produced during infections and is a well-known predictor of blood culture positivity in patients with sepsis." (PMID 39456869, 2024). "H. sampsonii has been reported to play an anti‐inflammatory role by inhibiting the secretion of inflammatory factors such as TNF‐α and IL‐6 in mice with LPS‐induced sepsis." (PMID 39312269, 2024). "In conclusion, Il-6 blockade with tocilizumab is a potential therapeutic strategy for severe sepsis/septic shock in children with febrile neutropenia." (PMID 38672594, 2024). "A dual-aptamer-based micromotor biosensing platform was designed for the simultaneous detection of procalcitonin (PCT) and interleukin-6 (IL-6) biomarkers, two critical indicators of sepsis." (PMID 39770207, 2024). "This suppression reduces the levels of TNF-α, IL-6, and IL-1β within the body during sepsis, diminishing the inflammatory response and sepsis-induced multiorgan dysfunction." (PMID 39234245, 2024). "Sphk1 expression is upregulated in peripheral blood monocytes of patients with sepsis, and studies have found that Sphk1 promotes inflammation and proliferation of glioblastoma through the NF-κB/IL-6/STAT3 signaling pathway." (PMID 38482014, 2024). "In acute stage of sepsis, the hyper-activated immune response including the increased IL-6, IL-1β and TNFα, as well as immune cell infiltration are the major causes for the multiple organ damages." (PMID 39726718, 2024). "The sepsis-proven group showed a significant increase in IL-6 levels from median baseline values of 7.5 pg/mL to 89.7 pg/mL on day −2, i.e., 2 days before clinical diagnosis." (PMID 38671704, 2024). "TNF-α, IL-1β and IL-6 belong to the most important systemic pro-inflammatory factors undergoing activation at the onset of sepsis." (PMID 39497013, 2024). "In a similar trial, sepsis patients with IL-6 levels > 1000 pg/mL were randomized to receive either afelimomab or placebo, without mortality effect (54% vs. 58%, n = 446)." (PMID 38807151, 2024). "Similar to previous studies, our ICU-sepsis group displayed significantly increased interleukin (IL)-18, IL-1β, IL-6, CXCL-8, IL-10 and MCP-1 compared to either or both of the ICU-non-sepsis patient and healthy cohorts." (PMID 38410714, 2024). "We monitored the progression of the inflammatory response by quantifying the clinical signs of systemic inflammation (mMSS), body temperature, and plasma IL-6 levels, a reliable biomarker of systemic inflammation and sepsis-related morbidity." (PMID 39266325, 2024). "HNF4α depletion in hepatocytes dramatically increases sepsis lethality, steatosis, and organ damage and prevents an adequate response to IL6, which is critical for liver regeneration and survival." (PMID 39261648, 2024).
Sepsis (continued). "In a prospective observational analysis, the combined measurement of PTX3, IL-6, PCT, and lactate demonstrated excellent predictive performance for 28-day all-cause mortality in patients with sepsis or septic shock, surpassing the SOFA score." (PMID 39201697, 2024). "Curcumin was found to improve survival and regulate proinflammatory cytokines (TNF-α, IL-6 and IL-1β) and anti-inflammatory cytokines (IL-2 and IL-10) in mice with sepsis/ALI induced by CLP." (PMID 39051370, 2024). "Overall, CLP sepsis strongly enhanced the IL-6 (> sixfold) (TNFα (> 23-fold), IL-1β (> twofold), IL-1ra (> 22-fold) MCP-1 (> 13-fold) gene expression in the hypothalamus." (PMID 39497013, 2024). "Other articles showed that the miR-31-5p/GSDMD Axis can regulate pyroptosis and miR-31-5p overexpressing can alleviate the level of TNF‐α, IL‐6 and IL‐1β in sepsis-induced pyroptosis." (PMID 38267979, 2024). "A meta-analysis showed that LMWH treatment in sepsis patients can reduce the expression of serum IL-6, TNF-α and other inflammatory factors, shorten prothrombin time, and improve coagulation." (PMID 39170046, 2024). "IL-6 is a key proinflammatory cytokine extensively studied for its role as an independent predictor of sepsis mortality." (PMID 39407738, 2024). "Nonetheless, besides the anti-inflammatory and regenerative activities of IL6, it also acts as a pro-inflammatory cytokine, making its protective role in sepsis controversial." (PMID 39261648, 2024). "We aimed to test the accuracy of IL-6 in neonates after 72 h of life in case of late onset sepsis (LOS)." (PMID 38671704, 2024). "In predicting mortality in the adult sepsis cohort, the logistic regression model identified systolic pressure, lactic acid, IL6, and NLR as the most important variables, followed by Tbil, PT, and RDW." (PMID 39835102, 2024). "Despite decreasing IL-6 values at all five time points, significantly higher values were found in the proven sepsis group than in the control group for all five measurement points." (PMID 38671704, 2024). "On the other hand, CRP and PCT were inferior to interleukin-6 (IL-6) predicting treatment success in 328 patients with sepsis when re-assessed after 48–72 h." (PMID 37204560, 2024). "Hepcidin also reduced macrophage IL-6 secretion, and when administered early, it reduced bacteremia in sepsis, thus demonstrating a protective role." (PMID 38368463, 2024). "When the anti-TNF Ab afelimomab was studied in a phase-III trial including sepsis patients using stratification, only patients with IL-6 levels > 1000 pg/mL had a reduced 28-day mortality (44% vs. 48%, n = 998)." (PMID 38807151, 2024). "In bacterial infectious diseases, such as septicemia, the increase of serum concentration of IL-1, IL-6, IL-8, IL-10, and TNF-α is generally earlier than the clinical manifestation of the newborn." (PMID 38848433, 2024). "We also confirmed the development and resolution of the systemic inflammatory response by measuring plasma levels of IL-6, a well-established biomarker of systemic inflammation and sepsis morbidity." (PMID 39266325, 2024). "Sepsis triggers a systemic inflammatory response, releasing pro-inflammatory cytokines like IL-6 and TNF-α, leading to endothelial dysfunction and increased vascular permeability." (PMID 39597864, 2024). "Sepsis is an uncontrolled systemic inflammatory response; inflammatory mediators such as TNF-α and IL-6 are elevated in sepsis, and it has been described that ER stress is dramatically induced in sepsis." (PMID 38672256, 2024). "Commonly used biomarkers for sepsis diagnosis, including C-reactive protein, procalcitonin, and interleukin-6, lack specificity for infection." (PMID 38396935, 2024). "This pathway is activated by IL-6/IL-6R (gp130) binding and influences cytokine expression in sepsis." (PMID 39367511, 2024).
Sepsis (continued). "It correlates positively with several inflammatory biomarkers, including CRP, IL-6 and TNFα, and has been investigated as a marker of kidney- and heart- injury, as well as sepsis." (PMID 38398274, 2024). "In Lorraine's research, the model constructed by plasma surfactant protein-D (SP-D), RAGE, IL-8, club cell secretory protein (CC-16), and IL-6 was helpful for diagnosing the occurrence of ARDS in patients with sepsis." (PMID 39319361, 2024). "Clinical predictive models have consistently shown that IL-6 holds favorable predictive value for sepsis severity and prognosis." (PMID 39835102, 2024). "In summary, our study emphasizes the significance of sTREM-1 as a critical biomarker for early risk stratification in sepsis, demonstrating strong correlations with APACHE-II scores and key biomarkers such as IL-6 and lactate." (PMID 39655134, 2024). "Due to inconsistent preclinical results, few clinical studies initially targeted IL-6 in classical sepsis." (PMID 39056754, 2024). "In terms of regulatory miRNAs, miR-26a-5p has been shown to protect against brain and myocardial IRI and alleviate sepsis-induced AKI via IL-6." (PMID 39715172, 2024). "On the other hand, inflammatory factors in sepsis, such as IL-6 and lactate, act on blood vessels, triggering the formation of thrombi and constriction of small blood vessels in sepsis." (PMID 38961249, 2024). "The failure of corticosteroids, anti-TNF-α, and anti-interleukin-6 monoclonal antibodies can be attributed to this altered EFA metabolism in sepsis." (PMID 38929553, 2024). "In the context of sepsis, inflammatory mediators such as TNF‐α, IL‐1, and IL‐6 are implicated in the activation of coagulation and the suppression of fibrinolysis by influencing the activation of the coagulation and fibrinolytic systems." (PMID 39445002, 2024). "For this reason, we phenotypically characterized the kinetics of the systemic response based on the clinical signs (MSS system) and the plasma IL-6 levels, which is a reliable well-established biomarker of systemic inflammation and sepsis morbidity." (PMID 39266325, 2024). "Since the liver is responsible for proinflammatory cytokine production and bacterial clearance during sepsis, we also examined IL-6 levels in liver homogenates." (PMID 38646937, 2024). "It is unlikely that this is only due to a pure dose effect of IL-6 (which is about four times higher in sepsis), as tocilizumab was administered in a saturating dose." (PMID 38598083, 2024). "Hepatic HNF4α LOF during sepsis, attributed to reduced chromatin binding, has implications for lipid metabolism and IL6-mediated APR downstream." (PMID 39261648, 2024). "The formation of ROS is enhanced by proinflammatory cytokines, such as interleukin-6 (IL-6) and tumor necrosis factor-alpha (TNF-α), contributing to organ harm associated with sepsis." (PMID 38629103, 2024). "Another study showed that a murine sepsis model induced by cecal ligation and puncture stimulated NF-κB1, TNFα, and IL-6 activation in the livers." (PMID 38603936, 2024). "Sepsis-induced cytokines, such as IL-6, TNF-α, and interleukin-1β (IL-1β), can directly affect the gut barrier by affecting intestinal cell proliferation and apoptosis." (PMID 39298039, 2024). "Activation of TLRs causes the release of pro-inflammatory cytokines, such as tumor necrosis factor (TNF-α) interleukins IL-1 and IL-6, resulting in a strong inflammatory response, leading to sepsis and septic shock." (PMID 38482014, 2024). "IL-6 is rapidly expressed (often within 2 h) by various cell types in response to infections and tissue injuries, playing a significant part in the sepsis-related systemic response to infection." (PMID 39202614, 2024). "We have shown that sepsis in mice activates the NLRP3 inflammasome, leading to the release of IL-1β, IL-6, and other cytokines and chemokines, causing cardiomyocyte (CM) dysfunction." (PMID 39201339, 2024).